ENSG00000281039 (novel protein)
Gene: Protein-coding gene on chromosome 7 (30,497,077 to 30,550,761, reverse strand). Ensembl gene ENSG00000281039.
Genetic constraint (gnomAD): Loss-of-function variants: 6 observed, 6.34 expected, observed/expected ratio (o/e) 0.95, 90% interval 0.51 to 1.73. That is too few expected variants to judge how well the gene tolerates losing a copy. Missense variants: 45 observed, 55.9 expected, observed/expected ratio (o/e) 0.81, 90% interval 0.63 to 1.03. Synonymous variants: 15 observed, 16.46 expected, observed/expected ratio (o/e) 0.91, 90% interval 0.61 to 1.4.